LINC00520 (long independently transcribed non-coding RNA 520)
Synonyms: LENT; LASSIE; LEENE; LncRNA00520; C14orf34
Gene: Long non-coding RNA gene on chromosome 14 (55,781,132 to 55,796,731, reverse strand). Ensembl gene ENSG00000258791.
Diseases named in the same sentence as LINC00520 in open-access papers:
LINC00520 is named in the same sentence as 29 diseases in open-access papers, as found by Europe PMC text mining. Sharing a sentence is not in itself a finding about the gene and the disease. The quoted sentences say what the papers report.
melanoma (12 papers, 2020 to 2025). A malignant, usually aggressive tumor composed of atypical, neoplastic melanocytes. "In this study, survival analysis revealed that LINC00520 was highly expressed in melanoma in the high-risk group, suggesting that the prognosis of this group was poor, but the conclusion still needs to be further verified." (PMID 36313708, 2022). "These demonstrated that high LINC00520 expression is an risk factor for the melanoma patients." (PMID 32466797, 2020). "The high expression of LINC00520 is closely related to the clinical stage of melanoma and survival rate of melanoma patients with high LINC00520 levels is lower than survival rate of patients with its low expression." (PMID 34638331, 2021). "In melanoma, several lncRNAs were recently reported to be associated with the initiation and progression of melanoma, such as SPRY4-IT1, Llme23, OVAAL, SRA, and LINC00520." (PMID 33311650, 2021). "LINC00520 has been widely reported in breast cancer, colorectal cancer, skin squamous cell carcinoma, melanoma, and other cancer cells, and shows increased expression in breast cancer tissue compared with normal breast tissue." (PMID 33854593, 2021). "LINC00520-FISH and qRT-PCR of nucleus and cytoplasm fragments showed that LINC00520 was distributed in both cytoplasm and nucleus in melanoma cells." (PMID 32466797, 2020). "Meanwhile, the level of LINC00520 in malignant melanoma cell (A375, A2058, CHL-1, MeWo, SK-MEL-28) was higher than that in human epidermal melanocytes (HEMa-LP)." (PMID 32466797, 2020). "LINC00520 has also been demonstrated to promote the proliferation, invasion and migration of melanoma cell." (PMID 32466797, 2020). "In conclusion, all results indicated that LINC00520 plays the pivotal role in the development of melanoma." (PMID 32466797, 2020). "Take together, these results demonstrated that LINC00520 promotes EIF5A2 expression by sponging miR-125b-5p in melanoma." (PMID 32466797, 2020). "LINC00520 facilitates the growth and metastasis of malignant melanoma by competitively binding to miR-125b-5p to liberate EIF5A2 mRNA transcripts, thereby promotes the EIF5A2 expression." (PMID 32466797, 2020). "We demonstrated that LINC00520 exerts its oncogene effect in melanoma by regulating Eukaryotic initiation factor 5A2 (EIF5A2)." (PMID 32466797, 2020). "We verified the RNA-seq results by detecting the expression of LINC00520 in 38 melanoma tissues and ANT, and found that LINC00520 was increased in melanoma tissues." (PMID 32466797, 2020). "Understanding the molecular mechanism of LINC00520 in melanoma is important to improve our knowledge of the molecular biological of malignant progression of melanoma." (PMID 32466797, 2020). "All results elucidated the role and molecular mechanism of LINC00520 in the malignant development of melanoma." (PMID 32466797, 2020). "The expression of LINC00520 in melanoma tissues were detected by using RNA-seq analysis and qRT-PCR." (PMID 32466797, 2020). "Take together, these results indicated that LINC00520 promotes the growth and metastasis of melanoma by decoying miR-125b-5p to promote EIF5A2 expression." (PMID 32466797, 2020). "In this study, we first analyzed the lncRNAs expression profile of melanoma tissue, and found that LINC00520 was increased in melanoma." (PMID 32466797, 2020). "In our melanoma patient samples, Kaplan-Meier analysis showed that the survival rate of melanoma patients with high LINC00520 levels was poorer." (PMID 32466797, 2020). "Scratch wound assays revealed that the migrative capacity of melanoma cells was suppressed by the LINC00520 siRNA." (PMID 32466797, 2020). "LINC00520 also promotes melanoma growth and metastasis in vivo by regulating miR-125b-5p/EIF5A2 axis." (PMID 32466797, 2020). "Furthermore, we found LINC00520 is an adverse prognostic factor for melanoma by multivariate Cox analysis, LINC00520 was reported to play roles in the occurrence and development of a variety of solid tumors, such as breast cancer." (PMID 36313708, 2022).
melanoma (continued). "Receiver operating characteristic (ROC) curves showed an area under the curve (AUC) >90.0% for KPNA2, DTL, BACE2, DTYMK, E2F3 and SLC25A13, >80.0% for CCNA2, FOXM1, KIF4A, SLC45A2, COPS8, SLC45A13 and 70.0% for CDC25A and LINC00520; all significantly discriminating melanoma from benign nevi." (PMID 36320118, 2022). "LINC00520 has been found to be overexpressed in melanoma tissues." (PMID 34638331, 2021). "Overexpression of LINC00520 can promote the proliferation, invasion, and migration of melanoma." (PMID 34250091, 2021). "Compared with normal melanocytes, LINC00520 was highly expressed in melanoma 38, and overexpression of LINC00520 could promote the proliferation, migration, and invasion of melanoma cells." (PMID 33854593, 2021). "We investigated the clinical significance of LINC00520 in melanoma patients." (PMID 32466797, 2020). "LINC00520 promoted the proliferation and metastasis of melanoma." (PMID 32466797, 2020). "LINC00520, a new oncogene in melanoma, maybe serve as a survival biomarkers or therapeutic target for melanoma patients." (PMID 32466797, 2020). "We discussed whether LINC00520 exerts its oncogenic effect in melanoma by regulating EIF5A2 expression." (PMID 32466797, 2020). "LINC00520 promotes the proliferation, invasion and migration of melanoma cells." (PMID 32466797, 2020). "All results suggested that LINC00520 directly binds to miR-125b-5p in melanoma." (PMID 32466797, 2020). "Also, LINC00520 (p-value = 0.00931) promotes the proliferation and metastasis of malignant melanoma by inducing the miR-125b-5p/EIF5A2 axis." (PMID 33392203, 2020). "Thereinto, the LINC00520 level was up-regulated 7.19-fold in melanoma tissues." (PMID 32466797, 2020). "We next explored the molecular mechanism of LINC00520 in melanoma." (PMID 32466797, 2020). "However, LINC00520 is a new oncogene in melanoma, of which the exact role and molecular mechanism in malignant melanoma remain unclear." (PMID 36313708, 2022). "Furthermore, the results of our multivariate Cox analysis suggested that the combination of DTL, LINC00520, ZSCAN16-AS1, XIST, and let-7a-5p could identify high-risk melanoma patients." (PMID 33854593, 2021). "These suggested that LINC00520 maybe participate in the malignant development of melanoma." (PMID 32466797, 2020). "We also domnostrated that the role of LINC00520 in melanoma cells is independent of BRAF mutation." (PMID 32466797, 2020). "We also found that miR-125b-5p inhibitor abolish the role of LINC00520 siRNA on the EIF5A2 expression, proliferation and metastasis of BRAF-WT melanoma cells." (PMID 32466797, 2020). "Finally, five predictive genes, ZSCAN16-AS1, LINC00520, XIST, DTL, and let-7a-5p were identified; these genes are closely related to the occurrence of melanoma." (PMID 33854593, 2021). "Moreover, we found that the inhibitory effect of LINC00520 siRNA on the EIF5A2 expression, proliferation, EMT, invasion and migration of melanoma cells were reversed by miR-125b-5p inhibitor." (PMID 32466797, 2020). "LINC00520 siRNA, miR-125b-5p mimic, miR-125b-5p mimic together with EIF5A2 plasmid and LINC00520 siRNA together with miR-125b-5p inhibitor were transfected into melanoma cells." (PMID 32466797, 2020). "The high expression of LINC00520 (expression ratio ≥ median ratio) is closely related to the clinical stage of melanoma, but not to age, sex, ulcer and family history." (PMID 32466797, 2020). "However, the exact role and molecular mechanism of LINC00520 in malignant melanoma has not been studied." (PMID 32466797, 2020). "However, the role of LINC00520 in malignant melanoma has not been studied until now." (PMID 32466797, 2020).
breast carcinoma (8 papers, 2016 to 2023). "The aim was to evaluate the association between the LINC00520 genetic polymorphisms and breast cancer (BC) susceptibility." (PMID 31997582, 2020). "In order to assess the biological role of LINC00520 in breast cancer, we performed shRNA-mediated loss-of-function studies in basal-like breast cancer cell lines containing endogenous levels of LINC00520." (PMID 27626181, 2016). "We further demonstrate that LINC00520 expression is clinically relevant and is preferentially associated with basal-like breast cancer." (PMID 27626181, 2016). "LINC00520, located on chromosome 14, is overexpressed in breast cancer, nasopharyngeal carcinoma and laryngeal squamous cell carcinoma and promotes the development of these cancers." (PMID 37516879, 2023). "Future studies will dissect the entire complement of LINC00520 biology and its significance in processes critical for breast cancer initiation and progression." (PMID 27626181, 2016). "To better understand this finding, we analyzed LINC00520 expression in breast carcinoma clinical samples." (PMID 27626181, 2016). "This analysis is consistent with the findings that LINC00520 modulates cell migration in breast cancer cell lines, a phenotype that is recapitulated in v-Src-transformed cells." (PMID 27626181, 2016). "By contrast, LINC00520 is downregulated upon depletion of PIK3CA in SUM159-PT (mutant PIK3CA H1047L) breast cancer cells." (PMID 27626181, 2016). "Here we identify and describe a novel lncRNA, LINC00520, and provide evidence for a potential role in breast cancer." (PMID 27626181, 2016). "We also investigate the transcriptional regulation of LINC00520 and provide evidence for its role in breast cancer development." (PMID 27626181, 2016). "Notably, expression of LINC00520 is increased in basal-like breast cancer cells, which also show a preferential increase in STAT3 activity." (PMID 27626181, 2016). "In this study, we provide evidence for a role for LINC00520 in breast cancer." (PMID 27626181, 2016). "Therefore, we next examined the expression of LINC00520 in a panel of breast cancer cell lines with defined genetic alterations and molecular subtypes." (PMID 27626181, 2016). "Furthermore, LINC00520 increases the expression of POSTN, CCNE2, or HSP27 by targeting miR-577, thereby accelerating the progression of breast cancer, non-small cell lung cancer, or colorectal cancer." (PMID 37516879, 2023). "Long intergenic non-protein coding RNA 520 (LINC00520), located on chromosome 14, has been reported to overexpress and function as a oncogene in breast cancer, nasopharyngeal carcinoma and laryngeal squamous cell carcinoma." (PMID 32466797, 2020). "Together, these findings characterize LINC00520 as a lncRNA that is regulated by oncogenic Src, PIK3CA and STAT3, and which may contribute to the molecular etiology of breast cancer." (PMID 27626181, 2016).
colorectal cancer (5 papers, 2021 to 2023). A primary or metastatic malignant neoplasm that affects the colon or rectum. "At the same time, the expressions of lnc-HOXC4-3:1, EFNA3, and LINC00520 were identified to be significantly related with the overall survival of colorectal cancer patients with P-values of 0.002, 0.008, and 0.021, respectively." (PMID 34262591, 2021). "LINC00520 promotes the progression of colorectal cancer by serving as a ceRNA for miR-577." (PMID 35242185, 2022).
glioma (5 papers, 2020 to 2022). A benign or malignant brain and spinal cord tumor that arises from glial cells (astrocytes, oligodendrocytes, ependymal cells). "Functionally, LINC00520 accelerated cell growth, invasion, migration and reduce cell apoptosis of glioma." (PMID 35945579, 2022). "LINC00520 knockdown inhibited glioma cell proliferation, migration, and invasion, but promoted apoptosis." (PMID 35309319, 2022). "miR-520f-3p, AP4, and LINC00520 therefore also form a feedback loop to mediate cancer progression in glioma." (PMID 33567514, 2021). "Recently, it was found thatAP4 binds to the promoter region of LINC00520, a novel lncRNA, and transactivates its expression in glioma cells." (PMID 33567514, 2021). "LINC00520 promotes the proliferation, migration and invasion of glioma cells, but inhibits its apoptosis." (PMID 32466797, 2020). "The study found that LINC00520 was up-regulated in glioma malignancies." (PMID 35309319, 2022). "A recent study reported a high expression of LINC00520 in glioma samples and cell lines." (PMID 35945579, 2022). "In gliomas, TFAP4-66aa-uORF inhibits the TFAP4/LINC00520/miR-520f-3p feedback loop by directly inhibiting TFAP4 expression, thereby attenuating glioma malignancies." (PMID 35309319, 2022). "In addition, transcription factors are also involved in the regulation of LINC00520, including SP1 in NSCLC, TFAP4 in glioma, and STAT3 in BC." (PMID 35309319, 2022).
acute kidney injury (4 papers, 2020 to 2023). Sudden and sustained deterioration of the kidney function characterized by decreased glomerular filtration rate, increased serum creatinine or oliguria. "LINC00520 sponging miR-27b-3p regulates OSMR expression to stimulate acute kidney injury via mediating the PI3K-Akt pathway." (PMID 33591944, 2021). "In addition, LINC00520 promotes the development of acute kidney injury by targeting miR-27b-3p and regulating OSMR expression through the PI3K/AKT signaling pathway." (PMID 37516879, 2023). "miR-27b-3p has been reported to be downregulated in acute kidney injury (AKI) and LINC00520 promotes the development of AKI by modulating miR-27b-3p/Oncostatin M Receptor β (OSMR) axis through the PI3K/AKT pathway." (PMID 33292252, 2020). "Besides, LINC00520 is significantly highly expressed in acute kidney injury (AKI)." (PMID 35309319, 2022).
nasopharyngeal carcinoma (4 papers, 2020 to 2025). A carcinoma arising from the nasopharyngeal epithelium. "LINC00520 affects the process of malignant progression of nasopharyngeal carcinoma by antagonizing the expression level of USP39 regulated by miR-26b-3p, suggesting that USP39 may play a role as a regulator in nasopharyngeal carcinoma." (PMID 40672756, 2025). "LINC00520 has been shown to play its role in nasopharyngeal carcinoma through the ceRNA mechanism." (PMID 32466797, 2020). "In contrast, in nasopharyngeal carcinoma, analysis by quantitative real-time fluorescence PCR (qRT-PCR) technology showed that LINC00520 was aberrantly expressed in tissues, and further analysis of clinical data indicated that LINC00520 may be associated with poor prognosis." (PMID 40672756, 2025). "Similarly, LINC00520 has been shown to play the same role in nasopharyngeal carcinoma." (PMID 32466797, 2020).
cutaneous squamous cell carcinoma (3 papers, 2021 to 2025). "Studies have also shown that LINC00520 inhibit the growth and metastasis of cutaneous squamous cell carcinoma." (PMID 37516879, 2023). "Interestingly, its expression level was found to be upregulated in most malignant tumors, but in cutaneous squamous cell carcinoma, LINC00520 expression was instead downregulated, suggesting that LINC00520 may have a dual regulatory role in tumors." (PMID 40672756, 2025).
breast tumors (1 paper, 2016). "Using RNA-sequencing data, we found that LINC00520 is upregulated in human breast tumors and it is particularly enriched in basal-like and HER2 intrinsic molecular subtypes." (PMID 27626181, 2016).
lung carcinoma (1 paper, 2022). "Generally, cancer patients with lower LINC00520 expression levels have a higher overall survival rate (OS), including lung cancer, LUAD, NSCLC, PTC, CRC, MM, and NPC." (PMID 35309319, 2022). "Knockdown of LINC00520 inhibited the proliferation, invasion, and migration of lung cancer cells." (PMID 35309319, 2022). "LINC00520 is highly expressed in lung cancer tissues and cells." (PMID 35309319, 2022). "In lung cancer, LINC00520 promotes the proliferation, invasion, and migration of cancer cells by inhibiting the expression of miR-3175 and inhibits cell apoptosis, thereby promoting the occurrence and development of lung cancer." (PMID 35309319, 2022).
lymph node metastasis (1 paper, 2019). "The relationship between the expression of LINC00520 and the clinical and pathological characteristics including clinical stage, pathological type, histological grade and lymph node metastasis of LSCC was analyzed." (PMID 31336999, 2019). "Interestingly, the LINC00520 level in LSCC with lymph node metastasis was significantly higher than that in patients without lymph node metastasis (p < 0.01)." (PMID 31336999, 2019).
metastatic melanoma (1 paper, 2021). A melanoma that has spread from its primary site to another anatomic site. "LINC00518 and LINC00520 were each found to be independent risk factors for metastatic melanoma patient survival and the network motif UCA1/hsa-miR-125b-1/AKT1 has an 88% chance of correctly identifying a TCGA sample as metastatic melanoma." (PMID 35008286, 2021).
osteoporosis (1 paper, 2023). A condition of reduced bone mass, with decreased cortical thickness and a decrease in the number and size of the trabeculae of cancellous bone (but normal chemical composition), resulting in increased fracture incidence. "LINC00520 functions as a modulator of calcium deposits, and exosomes derived from hucMSCs overexpressing LINC00520 might be a novel therapeutic approach for osteoporosis." (PMID 37516879, 2023).
triple-negative breast carcinoma (1 paper, 2016). An invasive breast carcinoma which is negative for expression of estrogen receptor (ER), progesterone receptor (PR), and human epidermal growth factor receptor 2 (HER2). "Interestingly, we find a preferential upregulation of LINC00520 in basal-like, triple-negative breast cancer cell lines, many of which display a high metastatic potential and poor prognosis." (PMID 27626181, 2016).